UHRF1 (ubiquitin like with PHD and ring finger domains 1)
Diseases named in the same sentence as UHRF1 in open-access papers (continued):
Sharing a sentence is not in itself a finding about the gene and the disease.
tumor (continued). "Collectively, the results of these studies have led to the proposal that UHRF1 is a tumor biomarker and therapeutic target for MM." (PMID 32213189, 2020). "Studies have found that the expression of UHRF1 in CRC is related to the depth of invasion of the tumor and that knocking down the expression of UHRF1 can inhibit the proliferation of CRC cells." (PMID 31803739, 2019). "Polyphenols have shown promising effects in downregulating the expression of UHRF1 and thereby reduce tumor cell proliferation." (PMID 31245293, 2019). "We found that the levels of acetylated histone H3 lysine 9 (H3K9ac) at the promoters of tumor-related genes remained low despite UHRF1 depletion, but they were increased by UHRF1 depletion plus TSA." (PMID 31064417, 2019). "In LIHC and THYM, our results showed a strongest correlation of UHRF1 expression and immune infiltration level, including tumor purity, B cell, CD8+ cell, CD4+ cell, macrophage, neutrophil and dendritic cell." (PMID 31442209, 2019). "On the other hand, UHRF1 promotes or does not affect proliferation of cells, especially in high proliferation capacity of tumor cells, and overexpression of UHRF1 notably actives proliferation, while downregulation of UHRF1 blocks proliferation." (PMID 31428652, 2019). "We also observed that UHRF1 expression significantly correlated with immune infiltration, and different types of tumor-infiltrating immune cells displayed different impacts on clinical outcomes." (PMID 31442209, 2019). "Data also showed a very significant increase in UHRF1 expression in tumor samples (fold-change mean: 20.4; p-value: 0.015)." (PMID 31249594, 2019). "To validate the association of UHRF1 with immune infiltration, we further evaluated the correlation between UHRF1 expression and 57 biomarkers from 16 subtypes of tumor-infiltrating immune cells in LIHC and THYM." (PMID 31442209, 2019). "When we investigated the expression levels of all three subunits of the trimeric repression complex, we found only UHRF1 to be overexpressed in primary tumor samples and HB cell lines when compared to normal liver tissue." (PMID 29507645, 2018). "The tumor size and average weight of tumors treated with UHRF1 depletion and docetaxel were much less than with the single treatment." (PMID 29752436, 2018). "In this study, we found that inhibition of UHRF1 suppressed tumor growth both in a cell culture condition and in a xenograft mouse model." (PMID 30174788, 2018). "UHRF1 plays a crucial role in the silencing of multiple tumor suppressor genes including p16(INK4A), thus promoting cell proliferation." (PMID 29899856, 2018). "The results showed that UHRF1 depletion significantly re-sensitized tumor xenografts containing docetaxel-resistant cells to docetaxel treatment." (PMID 29752436, 2018). "As immunostaining does not allow for a collective analysis for the whole tumor tissues, we used fresh tumor lysates to examine the expression level of UHRF1, XRCC4, and a few apoptosis markers." (PMID 29415984, 2018). "Overexpression of UHRF1 has been reported in a variety of human malignancies and is often predictive for higher tumor stages and poor patient outcome." (PMID 29507645, 2018). "Of note, when comparing UHRF1 expression levels with previously published expression levels of the tumor suppressor gene HHIP in primary tumor tissues and the three cell lines, we also found a significant inverse correlation of both genes (inset)." (PMID 29507645, 2018). "UHRF1 is an epigenomic regulator involved in multiple cellular processes that leads to tumor development." (PMID 29899856, 2018).
tumor (continued). "Like previous studies, overexpression of UHRF1 positively correlated with tumor size, staging and poor survival rate of patients." (PMID 28881702, 2017). "To examine the level of UHRF1 under endogenous hypoxic conditions that closely recapitulate the in vivo condition, we used a multicellular tumor spheroid model." (PMID 28584306, 2017). "As an epigenetic regulator, UHRF1 is known to contribute to tumor development by introducing changes in DNA and histone methylation by recruiting chromatin modifiers and thereby altering the gene expression." (PMID 28467809, 2017). "On the basis of these previous reports, it can be easily expected that the UHRF1 downregulation can effectively represses the tumor cell migration and invasion." (PMID 28584306, 2017). "On a cellular aspect, knockdown of UHRF1 inhibited the tumor growth in vivo and in vitro and induced cell cycle arrest at G2/M phase confirming the oncogenic potential of UHRF1." (PMID 28881702, 2017). "The purpose of our study was to determine if the expression levels of UHRF1 gene in patients with TCC correlates with the major pathological characteristics of the tumor and patient’s clinical outcome." (PMID 28128913, 2017). "UHRF1 expression is frequently found to be up-regulated in a variety of human tumour types and plays a central role in the hypermethylation of tumour suppressor genes." (PMID 28587163, 2017). "Collectively, it is reasonable to assume that UHRF1 upregulation is closely related with the development, growth and maintenance of the primary tumor." (PMID 28584306, 2017). "Using a xenograft model in nude mice, we discovered that tumor growth was significantly inhibited by UHRF1 knockdown, and IHC staining of the subcutaneous tumors showed that Ki-67 protein expression was significantly downregulated in sh-UHRF1-treated mice." (PMID 28060737, 2017). "Results were further confirmed by immunohistochemistry analysis of 136 HCC tissue samples which showed high expression of UHRF1 in tumor samples, positively correlating with tumor size, fetoprotein levels and HBV infection." (PMID 28881702, 2017). "These tumor-promoting functions of UHRF1 often involve its control of DNA methylation at tumor suppressors and other related genes in diverse cellular pathways." (PMID 28467809, 2017). "UHRF1 overexpression relates to tumor size, metastasis, α-fetoprotein, relapse and short survival time." (PMID 28881702, 2017). "The aim of our study was to determine if the expression levels of UHRF1 gene correlates with the major pathological characteristics of the tumor and patients’ clinical outcome." (PMID 28128913, 2017). "UHRF1 overexpression relates to poor differentiation, tumor stages,metastasis and low survival rate." (PMID 28881702, 2017). "Previous studies have indicated that UHRF1 promotes the proliferation of tumor cells, and downregulation of UHRF1 by RNA interference exerted a growth-promoting effect on tumor cells." (PMID 28060737, 2017). "The experiment indicated that the tumor growth speed in the UHRF1 Silence group was slower than that in the Blank group and NC group (P < 0.05)." (PMID 27431502, 2016). "The tumor in the UHRF1 Silence group was also thinner than that in the Blank group and the NC group (P < 0.05)." (PMID 27431502, 2016). "In agreement with this, it has been shown that UHRF1 overexpression in GC results from a reduction in the expression of miR-146a and miR-146b, which are known to act as tumor suppressors in GC." (PMID 27839516, 2016). "The results of nude mouse experiment indicated that tumor grow more slowly in UHRF1 silence group, implying that silencing UHRF1 can suppress the tumorigenesis of CaSKi cells in nude mouse." (PMID 27431502, 2016). "Our data demonstrated that miR-145-3p (the passenger-strand from pre-miR-145) had anti-tumor effects through targeting of UHRF1 in BC cells." (PMID 27072587, 2016).
tumor (continued). "The other studied target of miR-146a-5p, UHRF1, plays a role in cell cycle progression and is required for tumor cell growth, migration and metastasis." (PMID 26859141, 2016). "Nude mice tumor transplant experiment indicated that the growth rate and weight of tumor in the Blank group and NC group was higher and heavier than the UHRF1 Silence group (P < 0.05)." (PMID 27431502, 2016). "Taken together, all these findings show that miRNAs exert a fine tuning of tumor-suppressor expression via regulation of UHRF1 expression." (PMID 27839516, 2016). "Of note, matched PanIN lesions were available for eight UHRF1‐positive tumours; PanIN lesions express UHRF1 at variable but generally lower levels than matched tumours." (PMID 26497117, 2016). "Of 114 tumours positive for UHRF1, 94 (82%) were > 20 mm diameter, compared to 55% (10 of 18) of cases lacking UHRF1." (PMID 26497117, 2016). "The overall well admitted mechanism of tumor suppressor gene silencing is thought to be DNA methylation as almost all promoters of TGS regulated by UHRF1 are hypermethylated." (PMID 27839516, 2016). "This allowed us to assess the extent of DNA hypomethylation and effect on tumor growth controlled by negative regulation of DNMT3A by UHRF1/2." (PMID 27462454, 2016). "UHRF1 can influence the cell cycle control mainly through the epigenetic silencing of relevant tumor suppressors." (PMID 27437769, 2016). "This suggested that HELLS and UHRF1 depletion induce tumor growth inhibition through independent mechanisms." (PMID 25338120, 2014). "In the present work, we reported that the disruption of the DNMT1/PCNA/UHRF1 complex acts as an oncogenic event of the tumor transformation of brain (astrocytes), breast, lung and mesothelial cells." (PMID 24637615, 2014). "Using orthotopic human xenografts, we validated that upregulation of HELLS and UHRF1 is essential for the tumor phenotype." (PMID 25338120, 2014). "With respect to this domain, 280B is closely related to the protein UHRF1, which binds to methylated promoters of a number of tumor suppressor genes and can recruit histone acetyltransferases in its role in epigenetic regulation." (PMID 24236047, 2013). "UHRF1 upregulation is inversely correlated with PPARG expression in an advanced tumor stages CRC subgroup." (PMID 22848209, 2012). "The Dnmt1-immunoprecipitation indicated that it was the case because the quantity of PCNA and UHRF1 decreased when the tumor grade increased while the quantity of Dnmt1 immunoprecipitated remained unchanged." (PMID 20613874, 2010). "The RING domain of UHRF1 (Hs.108106) is a functional determinant of growth regulation and UHRF1 is generally required in tumor cell proliferation." (PMID 17559667, 2007). "Furthermore, immunohistochemical staining of tumour tissues was carried out to assess the expression magnitudes of proteins regulated by UHRF1." (PMID 40579780, 2025). "Notably, when PCA was repeated using only the six prognostic genes (AQP4, CDCA3, HJURP, KIF20A, PLK1, UHRF1), tumour and normal samples remained partially separable." (PMID 41007424, 2025). "Additionally, these findings further validate that simultaneous inhibition of both UHRF1 and DNMTs exhibits anti‐tumor activity by effectively suppressing the expression of NKX2‐5/LHX1." (PMID 40307990, 2025). "Additionally, E2F2, an active transcription factor in the DP and DN stages, upregulates the expression of UHRF1, resulting in hypermethylation of tumor suppressor genes." (PMID 40579780, 2025). "Notably, concurrent inhibition of UHRF1 and DNMTs impedes tumor growth by suppressing NKX2‐5 and LHX1 expression." (PMID 40307990, 2025). "Notably, the active E2F2 transcription factor in these stages upregulated UHRF1, enhancing the methylation of tumour suppressor genes." (PMID 40579780, 2025).
tumor (continued). "By investigating the role of epigenetic regulator UHRF1 and its mechanism in the methylation of tumour suppressor genes in malignant T cells, following intervention with azacitidine and decitabine, we assessed the effectiveness of demethylating therapy for T‐LBL." (PMID 40579780, 2025). "In the mouse primary CCA model, the overexpression of Stub1 and Uhrf1 individually promoted tumor progression, whereas the combined overexpression of both Stub1 and Uhrf1 further enhanced tumor progression, as demonstrated by the higher liver weight-to-body weight ratios observed in each group." (PMID 39267107, 2024). "At the mechanistic level, these detrimental effects of UHRF1 overexpression are mediated through multiple pathways, including alterations in exosome production, which likely contribute to intercellular communication favoring tumor progression." (PMID 39051184, 2024). "It is involved in the regulation of multiple tumor-related signaling pathways and immune cell microenvironment, suggesting that UHRF1 may be a potential molecular marker for prognosis prediction and targeted therapy of STS patients." (PMID 38847665, 2024). "Moreover, reduced UHRF1 expression impedes the G1/S cell cycle transition, resulting in decreased cell proliferation under experimental conditions and inhibited tumor growth in vivo." (PMID 39267107, 2024). "As implicated from the xenograft mice model, SIRT6 depletion enhanced tumor growth and angiogenesis, which could be significantly impaired by UHRF1-KD in UMUC-3 cells." (PMID 39709438, 2024). "Since previous work indicated that lactate could strengthen anti-tumor immunity by increasing CD8+ T cells in multiple tumor models, more immunological assays were warranted to confirm the associations between SIRT6/UHRF1 and immune evasion in BLCA." (PMID 39709438, 2024). "Additionally, IHC assays demonstrated that Stub1 and Uhrf1 enhanced the expression of Ki67 in tumor cells." (PMID 39267107, 2024). "In TNBC, UHRF1 overexpression has enhanced tumor growth through the induction of angiogenesis." (PMID 39051184, 2024). "This difference in expression of c-Myc and UHRF1 in tumor and normal cells might suggest that SKF83566 has a therapeutic window by selectively inhibiting GBM invasion and cell stemness." (PMID 38246990, 2024). "While hinokitiol reduces the expression of both UHRF1 and GLI1, it remains unclear whether the tumor-suppressing function of hinokitiol is solely dependent on UHRF1 inhibition." (PMID 37380646, 2023). "This may indicate that UHRF1 is essential for the initial phases of KRAS-driven tumor growth, while the maintenance of spheroid growth may be less directly dependent on UHRF1 activity." (PMID 37407562, 2023). "Moreover, UHRF1 functions as an epigenetic regulator, the depletion of which reprograms liver CSCs toward differentiation and tumor suppression via Hedgehog/GLI1 and Wnt signaling." (PMID 37380646, 2023). "This suggests that the observed anti-tumor effect of UHRF1 depletion is, at least partially, mediated by its role in DNA methylation, and that DNMT1 inhibition may mimic the effect of UHRF1 loss." (PMID 37407562, 2023). "Here, we show that UHRF1 KO decreases clonogenicity and tumor growth both in vitro and in vivo." (PMID 36068209, 2022). "Thus, TAM PGE2 and tumor UHRF1 form a positive circuit, which contributes to cultivating a potent inflammatory microenvironment." (PMID 35664070, 2022). "In line with our previous data, silencing UHRF1 reduced tumor growth and prolonged mouse survival." (PMID 35664070, 2022). "The results showed that tumor tissue had higher expression level of UHRF1 than usual tissue." (PMID 35656341, 2022). "The pro-tumor effect of ectopic UHRF1 was abolished by KLF6 overexpression." (PMID 35664070, 2022).
tumor (continued). "Along this line, our data demonstrates that high HCC UHRF1 causes increased tumor CSF1 production by reducing DNMT1-mediated DNA methylation in the CSF1 promoter; subsequently, tumor CSF1 promotes TAM tumor infiltration and boosts TAM COX-2 expression and PGE2 production." (PMID 35664070, 2022). "Future studies on UHRF1 expression and tumor immune microenvironment and methylation may provide new strategies for tumor immunotherapy." (PMID 35656341, 2022). "Furthermore, addition of PGE2 neutralizing monoclonal antibody (anti-PGE2 mAb) into TAM supernatants abolished upregulated UHRF1 expression in tumor cells." (PMID 35664070, 2022). "The data suggest a mutually enforced interaction between macrophages and tumor UHRF1 in HCC." (PMID 35664070, 2022). "In addition, macrophages efficiently migrated toward the culture supernatants from enforced UHRF1-expressing tumor cells compared to the controls." (PMID 35664070, 2022). "miR-9 and miR-202 serve as tumor suppressors and attenuate cell migration through UHRF1 blockage." (PMID 35087589, 2022). "Several miRNAs can control UHRF1 expression in different neoplasia." (PMID 35087589, 2022). "Western blot confirmed high levels of CSF1 and CCL14 protein in UHRF1 expressing tumor cells." (PMID 35664070, 2022). "By regulating UHRF1, the pre-miR-145 and guide strand miR-145-5p and passenger strand miR-145-3p act as anti-tumor miRNA in BLCA, thus indicating that both the guide and passenger strands of miRNA have a biological role through the regulation of several genes in BLCA." (PMID 33672684, 2021). "Since the TTD is responsible for recognizing the H3K9me3 inhibitory histone marks, we envision potent TTD inhibitors may stimulate tumor suppressor genes expression through blocking UHRF1 from binding to the H3K9me3 inhibitory marks on their promoters." (PMID 33441849, 2021). "Furthermore, while immunohistochemistry (IHC) analysis revealed cytoplasmic localization of β-catenin in normal tissues, IHC detected obvious nuclear localization of β-catenin in tumor tissues from both Uhrf1+/+/ApcMin/+ and Uhrf1ki/ki/ApcMin/+ mice." (PMID 33947834, 2021). "Importantly, comparison of Uhrf1+/+/ApcMin/+ and Uhrf1ki/ki/ApcMin/+ mice revealed a substantially reduced tumor burden in Uhrf1ki/ki/ApcMin/+ mice." (PMID 33947834, 2021). "Additionally, overexpression of miR-124 in vitro attenuated cellular proliferation, migration, invasion, and angiogenesis, while in vivo tumor growth downregulated UHRF1, showing an inverse relationship between miR-124 and UHRF1." (PMID 33672684, 2021). "Similarly, UHRF1 also acts as an antioncogene in multiple cancers and inhibits tumor development and progression." (PMID 34398824, 2021). "We found that Uhrf1-TTD-KI mice had a much lower tumor burden than wild-type mice." (PMID 33947834, 2021). "In addition, there was also a significantly higher level of apoptosis in the tumor tissues from Uhrf1ki/ki/ApcMin/+ vs. Uhrf1+/+/ApcMin/+ mice." (PMID 33947834, 2021). "Following the 2 weeks' treatment, tumor‐burdened eyes were analyzed for average tumor area to determine whether UHRF1 depletion would affect the therapeutic efficacy of MS‐275." (PMID 31782885, 2020). "High expression of UHRF1 in tumor tissues has been reported to promote tumor metastasis." (PMID 31803739, 2019). "Besides, UHRF1 has been extensively studied in tumor pathogenesis, and UHRF1 can maintain methylation status of tumor suppressor genes." (PMID 31428652, 2019). "These difference induced by RP11-424C20.2/UHRF1 axis may contribute to the change of tumor-immune microenvironment and development of LIHC and THYM." (PMID 31442209, 2019).